NEDD8 (NEDD8 ubiquitin like modifier)
Diseases named in the same sentence as NEDD8 in open-access papers (continued):
Sharing a sentence is not in itself a finding about the gene and the disease.
cancer (65 papers, 2013 to 2026). A tumor composed of atypical neoplastic, often pleomorphic cells that invade other tissues. "In BLCA, the neddylation-associated protein developmentally downregulated 8 (NEDD8) was found to be overexpressed in cancer tissues and correlated with reduced patient survival." (PMID 40524221, 2025). "This binding effectively blocks the NEDD8 pathway, causing cancer cells to undergo apoptosis by lowering cellular levels of NEDD8 and accumulating UBC12, a downstream target." (PMID 41181006, 2025). "Deficiency of NEDD8 protein in TNBC cancer cells alters immunogenicity that leads to potent immune response after ICB therapy." (PMID 38678024, 2024). "It has been shown that NEDD8 and neddylation enzymes are overexpressed in a variety of human cancers, which is associated with poor survival of cancer patients." (PMID 40440083, 2024). "Since neddylation is frequently associated with malignant evolution in cancers, targeting the NEDD8 conjugation pathway through the inhibition of its activating enzyme by MLN4924 was developed as a new anticancer strategy." (PMID 36890567, 2023). "Intensive studies have proven that NEDD8 and enzymes of neddylation pathway (e.g. NAE1/UBA3, UBE2M/UBE2F and NEDD8 E3 ligases) are often overexpressed in multiple human cancers, which is associated with disease progression and predicts poor patient survival." (PMID 30943988, 2019). "We reveal that NEDD8 loss in cancer cells causes a vulnerability to nivolumab (anti-PD-1)." (PMID 38678024, 2024). "Furthermore, overexpression of NEDD8 is observed in cancer cells and causing aberrant proliferation, apoptosis, or migration." (PMID 38177106, 2024). "Furthermore, the dysregulation of many key substrate proteins of CRLs regulated by NEDD8 is associated with cancer." (PMID 35408841, 2022). "Therefore, the NEDD8 pathway is implicated in the control of multiple cancer-related biological processes." (PMID 27901050, 2016). "Finally, we note that because NEDD8 pathway components are overexpressed or mutated in many human cancers, NEDD8-pathway inhibition is a promising anti-cancer strategy." (PMID 25921528, 2015). "Therefore, it can be speculated that the loss of NEDD8 triggers cellular reprogramming and the ubiquitination system becomes indispensable in cancer cells." (PMID 38678024, 2024). "Neddylation is a posttranslational modification in which the ubiquitin-like protein NEDD8 is added to substrate proteins and has been recognized to modulate tumorigenesis and influence components of the tumor microenvironment, such as immune cells and cancer-associated fibroblasts (CAFs)." (PMID 36564767, 2022). "More importantly, depleting or inhibiting NEDD8 can be an efficient strategy to reduce cancer metastasis after surgery resection by regulating the function of Tregs." (PMID 38177106, 2024). "In the current study, we investigated the role of NEDD8 in surgical stress-facilitated cancer metastasis and the involvement of Tregs, and revealed the underlying mechanisms." (PMID 38177106, 2024). "In 1998, researchers found that both cullin protein and NEDD8 were highly expressed in various cancer cell types, such as colon cancer and leukemia cells, thereby reinforcing the association of neddylation with cancer progression." (PMID 38191508, 2024). "The NEDD8 pathway regulates many cancer-related processes, including cell cycle progression, DNA replication, and repair, and is upregulated in tumours." (PMID 39404389, 2024). "Suppression of cell migration and invasion are key effects related to the anti-cancer properties of NEDD8 inhibitors or of natural medicinal compounds such as the alkaloid Sanguinarine." (PMID 39404389, 2024). "NEDD8 depletion can be effective in suppressing postoperative cancer metastasis by recovering the anti-tumor immunity." (PMID 38177106, 2024). "To examine the mechanistic insights of NEDD8 in cancer immunogenicity, we re-expressed a truncated form of the NEDD8 protein in MDA-MB-231 KO cells, i.e., NEDD8-T." (PMID 38678024, 2024).
cancer (continued). "Numerous anti-cancer factors and pro-cancer factors are directly modified by NEDD8, and certain neddylation substrates such as CRL, EGR1, and HIF-1α can simultaneously regulate both types of factors." (PMID 39062453, 2024). "It is therefore surprising that only few studies addressed the prognostic relevance of NEDD8 expression for the outcome of cancer patients thus far." (PMID 38672281, 2024). "For example, human epidermal growth factor receptor 2 (HER2), correlated with poor prognosis in breast cancer, was found to accelerate cancer progression in a NEDD8-dependent manner." (PMID 39062453, 2024). "Given that NEDD8 in Tregs was increased upon surgical stress, we then examined the effect of NEDD8 knock out on Tregs to investigate how NEDD8 regulates Tregs during surgical stress-induced cancer metastasis." (PMID 38177106, 2024). "Altogether, it is suggested that NEDD8 is essential for Treg-mediated immunosuppression, which is adverse to cancer metastasis." (PMID 38177106, 2024). "For example, WD Repeat Domain 70 (WDR70) and NEDD8 ubiquitin-like modifier (NEDD8) are both essential genes in multiple cancer lines." (PMID 37845222, 2023). "Recently, a small-molecule pevonedistat, also named MLN4924, was developed to inhibit NEDD8-mediated neddylation and appeared to effectively suppress tumor growth in several cancer types." (PMID 36890567, 2023). "Post-translational modifications by ubiquitin and ubiquitin-like proteins SUMO or NEDD8 are described in a multitude of cellular processes and are essential in cellular pathways and functions that are often dysregulated in cancer." (PMID 35408841, 2022). "When samples from all tumor types were included, there was a slight, but significant, positive correlation between UBA1 and NEDD8 expression (R = 0.134), which would suggest that in many cancers as NEDD8 levels increase there is also an increase in UBA1." (PMID 34685640, 2021). "Recently, the neddylation pathway, including its three enzymes NAE, UBC12 and NEDD8, has been reported to be overactivated in many kinds of cancer cells, indicating the neddylation pathway as a promising anticancer target." (PMID 33898327, 2021). "To simplify the analysis and look for statistical significance, we compared levels of UBA1 expression with NEDD8 to determine if there was a correlation both in the pan-cancer dataset as well as specific tumor types." (PMID 34685640, 2021). "Accumulating evidence shows that NEDD8 is overexpressed in some human diseases, such as neurodegenerative disorders and cancers." (PMID 33898451, 2021). "Neural-precursor-cell-expressed developmentally down-regulated 8 (NEDD8) is an ubiquitin-like protein involved in various DNA repair mechanisms and causes synthetic lethality to cancer cells." (PMID 34209457, 2021). "NAE is an essential protein in the NEDD8 conjugation (neddylation) pathway, affecting cancer cell growth and survival through activation of CRLs." (PMID 33560503, 2021). "Mdm2/NEDD8/HuR axis plays an important role in liver malignant transformation and tumor progression, potentially amenable for cancer therapy." (PMID 33513829, 2021). "We further confirmed both the migration effects and expression levels using si-NEDD8 and treating with the same inhibitors in all three cancer cell lines." (PMID 33097763, 2020). "To identify the role of NEDD8 in cancer progression, we examined NEDD8 mRNA expressions in three different types of cancers." (PMID 33097763, 2020). "The neddylation process was inhibited by transfecting cancer cells with NEDD8-targeting siRNAs or by treating the cells with a NAE1 inhibitor MLN4924." (PMID 29301501, 2018). "NEDD8 seems to inhibit the Src-mediated phosphorylation of caveolin-1 by modifying the structure of caveolin-1 protein, which blocks the migration of cancer cells." (PMID 29301501, 2018).
cancer (continued). "Our functional studies revealed that knockdown of NEDD8 expression suppressed cancer cell proliferation, colony formation and NPC cell stemness characteristics such as self-renewal, tumorigenesis, radiation, and drug resistance." (PMID 28569775, 2017). "NEDD8 affected cancer stem cell phenotypes of NPC as assessed in vitro using the cell number of side population (SP) by flow cytometry analysis, colony formation assay, sphere formation assay, and tumor initiation ability in vivo." (PMID 28569775, 2017). "These NEDD8 E3s will probably have unique functions in these tissues that are impossible to study in cancer cell lines." (PMID 26906416, 2016). "By using MLN4924, an anti-cancer drug in clinical trials that specifically inhibits conjugation of the ubiquitin-like protein, NEDD8, to target proteins, we demonstrate that NEDD8 accumulation at DNA-damage sites is a highly dynamic process." (PMID 25921528, 2015). "Up-regulation of NEDD8-catalyzing enzymes (E1/E2/E3) and/or global protein neddylation in human cancer further highlights the important role of neddylation in cancer." (PMID 25797246, 2015). "Protein modifications by NEDD8 have important functions promoting cancer cell survival as discovered from pre-clinical studies using the first-in-class NAE inhibitor MLN4924." (PMID 24691136, 2014). "This inhibitor, MLN4924 (Millenium Pharmaceuticals), has led toward development of an anti-cancer drug targeting the NEDD8 pathway that is currently in clinical trials." (PMID 23825614, 2013). "Additionally, it examines therapeutic strategies targeting NEDD8 modification, offering novel avenues for innovative cancer treatments by disrupting this dynamic, reversible modification process." (PMID 41540013, 2026). "In addition, the increased expression of NEDD8-conjugated proteins has been observed in some MLN4924-resistant cancer cells." (PMID 38191508, 2024). "The activation of NK cells by NEDD8 KO TNBC cancer cells showed only a trend of increase." (PMID 38678024, 2024). "Our observations suggest that cancer progression may result from surgery-induced enhancement of NEDD8 expression and the subsequent immunosuppressive function of Tregs." (PMID 38177106, 2024). "The initial non-Cullin proteins implicated as substrates in NEDD8 research, were associated with Breast Cancer-Associated protein 3 (BCA3), a yeast-derived protein." (PMID 38191508, 2024). "NEDD8/neddylation blockade may break Treg-mediated immune tolerance, restore the anti-tumor response and improve prognosis of cancer patients after surgery." (PMID 38177106, 2024). "Indeed, overactivation of CRLs has been characterized in tumor growth and progression and the enzymes implicated in the neddylation pathway (e.g., NAE1/UBA3, UBE2M/UBE2F, NEDD8 E3 ligases) are often overexpressed in different human cancers, including MM." (PMID 37460534, 2023). "This revealed 11 samples across six different cancer types with a nonsynonymous mutation in a neddylation-associated gene: four with a UBE2M mutation, five with a NAE1 mutation, one with a NEDD8 mutation, and one with a mutation in the NEDD8-binding domain of CUL3." (PMID 36068196, 2022). "Neural precursor cell expressed developmentally downregulated-8 (NEDD8) is a ubiquitin-like molecule that can be transferred to substrates to regulate protein function through a process termed protein neddylation, and Nedd8 is expected to play a role as a therapeutic target in cancer." (PMID 36569748, 2022). "Although the neddylation of proteins in human cells is inevitable, overexpression of NEDD8 may trigger abnormal effects in cells, leading to the development of cancer." (PMID 34571823, 2021). "Intensive studies have proven that NEDD8 and enzymes of the neddylation pathway (e.g., NAE1/UBA3, UBE2M/UBE2F, and NEDD8-E3 ligases) are often overexpressed in multiple human cancers, which are associated with tumor progression and predict poor patient survival." (PMID 33184273, 2020).
cancer (continued). "Since Nedd8 is a key regulator of cell growth, viability and malignant transformation, neddylation inhibition could prove to be an effective anti-cancer therapy." (PMID 25650664, 2015). "In agreement with this hypothesis, several cancers have shown increased NEDD8 expression and over-activated cullin-RING ligases (CRLs), whose activation is dependent on NEDD8 attachment, suggesting that NEDDylation is closely related to tumorigenesis." (PMID 26692264, 2015). "Recently, the NEDD8 pathway has become an important target for cancer therapy." (PMID 26497688, 2015). "In addition, as neddylation upregulation is found in many human cancers, the NEDD8 pathway may be considered a novel therapeutic target." (PMID 36291779, 2022). "Additionally, other studies have suggested that NEDD8 abrogation may boost carcinogenesis and drug resistance, which has encouraging implications for the development of NEDD8 pathway-regulation strategies for cancer therapy." (PMID 30586948, 2018). "MLN4924, a newly developed selective inhibitor of NEDD8 (neural precursor cell expressed developmentally downregulated 8)-activating enzyme, can disrupt CRL-mediated protein turnover leading to apoptotic death in human cancer cells, while its use caused fewer side effects." (PMID 28576144, 2017). "Because immune activation relied on allogeneic antigens presented by cancer cells in TICS, we decided to validate the cancer intrinsic role of the Nedd8 gene using syngeneic mouse models." (PMID 38678024, 2024). "The NEDD8 inhibitor MLN4924 (Pevonedistat), which selectively targets the NEDD8 E1-activating enzyme, has shown a strong anti-cancer response in pre-clinical studies and is now in Phase III clinical trials." (PMID 39404389, 2024). "We then validated the endogenous interaction between NEDD8 and IRS1 as well as IRS2 in all three cancer cell lines, affirming the neddylation E3 ligase function of C-CBL." (PMID 38272982, 2024). "This review explains the relationships between NEDDylation and cancers, structural characteristics of NAE and multistep mechanisms of NEDD8 activation by NAE." (PMID 37525282, 2023). "Consistent with previous studies, we found that NEDD8 was elevated in HNSCC compared with normal tissues, possibly owing to a more active UPS system and metabolism in cancer cells." (PMID 37689760, 2023). "Recent studies from our and other groups demonstrate that protein neddylation (NEDD8 and NEDD8-conjugated proteins) and the key components of the neddylation pathway (NAE, UBE2F, UBE2M, RBX1, RBX2) are overactivated in multiple human cancers." (PMID 34164400, 2021). "Another example includes its involvement in the regulatory framework with Mdm2 and NEDD8, inducing growth advantage in HCC cancer cells." (PMID 33513829, 2021). "Using PC3 (prostate), H1299 (lung), and SKOV3 (ovarian) cancer cell lines, we assessed cell migration via both wound healing assay and transwell assay by using MLN4924 and NEDD8-targeting siRNA (si-NEDD8)." (PMID 33097763, 2020). "Similarly, the NEDD8 E3 ligases, DCN1 and RBX1/2, are also up-regulated in several types of human cancer types." (PMID 35880551, 2022). "A recent study demonstrated that NEDD8 can directly bind to a variety of destabilized, non-canonical, substrates present in cancers characterized by microsatellite instability." (PMID 34685640, 2021). "Herein, the metabolic slowdown observed after neddylation inhibition was due to the negative impact that the absence of Nedd8 has in the OXPHOS pathway ending in cancer cell apoptosis." (PMID 25650664, 2015).
cancer (continued). "Therefore, inhibition of the NEDD8-mediated clearance pathway leads to the buildup of misfolded protein aggregates, which triggers immunogenic cell death and enhances the efficacy of PD1 inhibition in dMMR cancers." (PMID 41540013, 2026). "NEDD8, a ubiquitin-like small protein, has been identified as a regulator of the activity of a group of E3 enzymes within the ubiquitin-proteasome system, including the cullin-RING E3 ubiquitin ligases (CRLs), which control the turnover of several proteins involved in cancer biology." (PMID 33560503, 2021). "Therefore, the therapeutic targeting of protein SUMOylation may represent a novel approach for the treatment of myriad cancers, including GBM; interestingly recent reports have also emerged demonstrating that elevations in the conjugation of NEDD8 are involved in the pathogenesis of GBM34." (PMID 28785061, 2017). "Given the clear negative impact of NAE inhibitors on immune cells and cancer immunogenicity due to off-target effects, we decided to employ CRISPR/Cas9 to specifically target the Nedd8 gene in murine cancer cells for in vivo studies." (PMID 38678024, 2024). "Specifically, NUB1/NUB1L non-covalently binds to NEDD8 through their UBA domains to prevent its aberrant effects in cells and, ultimately, the development of cancer." (PMID 34571823, 2021). "However, in certain cancer types, there were statistically significant negative correlations between UBA1 and NEDD8 expression, including colon and rectal cancers (R = −0.1414) and lung adenocarcinoma (R = −0.1983)." (PMID 34685640, 2021).